CD4 (CD4 molecule)
Diseases named in the same sentence as CD4 in open-access papers (continued):
Sharing a sentence is not in itself a finding about the gene and the disease.
infection (continued). "During chronic infection they could cause the deregulation of HIV-specific response, so favoring the progression of the infection, and a decrease of such cells has been associated to an increase in CD4+ and CD8+ specific responses to the virus." (PMID 23236388, 2012). "Highly active ART (HAART) instituted during early infection could alleviate CD4 loss, suppress viremia, and limit the size of the latent reservoir." (PMID 22479485, 2012). "The remarkable decrease of CD4+ T cells, including Treg cells, during the acute phase of infection may contribute to the loss of immunological memory that are often observed in vaccine studies and recurrent human infection." (PMID 22905277, 2012). "CD4+ T-cell responses to heterologous DBLα-tags probably reflect previous or concurrent exposure of individual children to PfEMP1 variants with similar DBLα-domains either during the current or a previous infection." (PMID 22272280, 2012). "Moreover a Cox proportional hazard model demonstrated a significantly increased risk of CD4 counts falling below both 350 (HR 2.36) or 300 (HR 3.80) over the first three years of infection for individuals whose gag gene conferred an RC>2 vs. RC<1." (PMID 23209412, 2012). "One of the highly pathogenic SHIV strains, SHIV-KS661, which has the env gene of HIV-1 89.6 and predominantly uses CXCR4 as the secondary receptor for its infection, causes an infection that systemically depletes the CD4+ T cells of rhesus macaques within 4 weeks after infection." (PMID 22364292, 2012). "While the overall recruitment of CD4 T cells into the skin was reduced in CCR6-deficient mice cytokine producing cells were more frequent indicating that the tendency towards inflammation was set early after infection in B6.CCR6−/− mice." (PMID 23028548, 2012). "NK cells also regulate CD4 responses during LCMV Armstrong infection of CD8 T cell-deficient mice." (PMID 23248626, 2012). "Highly active antiretroviral therapy (HAART) can suppress HIV-1 replication and normalize the chronic immune activation associated with infection, but restoration of naïve CD4+ T cell populations is slow and usually incomplete for reasons that have yet to be determined." (PMID 22241988, 2012). "Infection-associated immune activation may also decrease receptor density, since CD4 is down-regulated with T-cell activation." (PMID 23237529, 2012). "Resolved infection was associated with CD4 T cells targeting NS proteins." (PMID 22337948, 2012). "In general, a CD4+ T-cell count of <200/mm3 puts the patient at risk for a prolonged infection, and counts of <100/mm3 may result in an even more severe life-threatening diarrhea." (PMID 22685452, 2012). "Indeed, CD4 cell count decline and viral load rise are associated with longer duration of infection and natural disease progression." (PMID 23031662, 2012). "Using a Cox proportional hazard model, we demonstrate a significantly increased risk of CD4+ T cell counts falling below 350 (Hazard Ratio (HR) 2.36; p = 0.034) or 300 (HR 3.80; p = 0.021) over the first three years of infection for individuals whose Gag conferred an RC>2 vs. RC<1." (PMID 23209412, 2012). "To test this hypothesis, we examined the effect of cannabinoid receptor activation on HIV viral transmission and productive infection in CD4+ T cells using a GFP-expressing, CXCR4-tropic HIV-1 variant." (PMID 22448282, 2012). "It has indeed been previously reported that Rag2−/−γc−/− mice conditioned with TBI and transplanted with human CD34+ cells sustain high-titer infection persisting more than one year and associated with a slower decline of CD4 T cells after inoculation of an R5 strain." (PMID 22675567, 2012). "Surprisingly, CrNA is also associated with lower CD4 T cell counts early in infection." (PMID 22833745, 2012). "CD4+ T cell subsets have different activation and coreceptor expression levels, and thus may be differentially susceptible to infection by T/F versus chronic control viruses." (PMID 22693444, 2012).
infection (continued). "Infection with highly replicating variants could lead to a more complete depletion of central memory CD4+ T cell pools at this early time that could predispose an individual to more rapid CD4+ T cell loss, irrespective of adequate control of viral replication." (PMID 23209412, 2012). "Moreover, adoptive transfer of the virus-specific antibody produced by infected CD4 T-cell-deficient mice protected B-cell-deficient mice from infection by reducing tissue viral loads." (PMID 23133489, 2012). "In Foxp4 cKO mice, the reduced IFNγ production in response to STAg forty days post-infection may be caused by defects in CD4 T cell help." (PMID 22912696, 2012). "Since the infection of TLR2/4 double-deficient mice with C. pneumoniae generated even more CD4+IFNγ+ T-cells, we conclude that in vivo antigen-presenting cells are not impaired in their ability to activate antigen-specific T-cells in the absence of TLR2 and TLR4." (PMID 22096480, 2011). "Our study is the first one, which quantified APOBEC3 mRNA in the context of an immunodeficiency virus infection not only in whole PBMC, but also in leukocyte subsets susceptible to infection such as CD4+ T-cells and CD14+ monocytes as well as in the lymph nodes as major virus replication sites." (PMID 21955401, 2011). "The inability of Irgm1-/- NR1 cells to expand to similar numbers as wildtype NR1 cells at the site of the infection could be explained by the propensity of Irgm1-deficient mature CD4+ T cells to prematurely die when activated for proliferation." (PMID 21731484, 2011). "However, when these cells were engineered to express CD4, HeLa/CD4 cells were found to be as susceptible to the CD4-dependent mNDK vector infection as 293T/CD4 and TE671/CD4 cells." (PMID 21541353, 2011). "Infection by HIV-1 causes a profound depletion of CD4+ T cells." (PMID 21284901, 2011). "Therefore, we evaluated the loss of peripheral blood CD4+ T cells and central memory (CM) CD4+ T cells on days 14 (peak) and 70 (set-point) following SIVmac251 infection in these monkeys." (PMID 22194686, 2011). "These exclusive epitopes may be related to some particularities of the infection caused by this Leishmania species, perhaps contributing to the stimulus of sub-populations of CD4+ T cells related to pathogenesis." (PMID 21824434, 2011). "Moreover, spinoculation was used for in vitro infection assays, a method which enhances infection efficiency and has recently been implicated in enhanced CD4 and co-receptor expression due to cytoskeletal activation in T cells." (PMID 22163344, 2011). "However, upon infection TLR2/4 double-deficient mice displayed a lower frequency of CD4+CD25+Foxp3+ regulatory T-cells in vivo and the frequency of regulatory T-cells was inversely related to the frequency of CD4+IFNγ+ T-cells." (PMID 22096480, 2011). "This preferential binding to alpha-4 beta-7 cells is thought to be an important factor in concentrating early viral replication in the intestinal tract of infected individuals, leading to the massive loss of CD4 T cells within this compartment in the first few weeks of infection." (PMID 21284905, 2011). "Patients with HIV and low CD4 counts presents a particular challenge in the interpretation of 18F-FDG PET/CT scans as a variety of infections and malignancies may cause increased FDG uptake." (PMID 21955517, 2011). "Over-expression of conventional and T helper response cytokines shows the potency of stimulated DCs to prime and induce expression of Th1-, Th2- and Th17-related cytokines by CD4+ T cells, and regulate the inflammatory response associated to that kind of infection." (PMID 21857913, 2011). "The hypoergic status of CD8 T cells and the increased susceptibility of CD4 T cells to apoptosis may be induced by specific cytokines produced during infection to avoid an immunological response against Koch's bacillus." (PMID 22111973, 2011). "Infection with HIV-1 leads to chronic viremia with a resultant CD4 T cell loss." (PMID 21695116, 2011).
infection (continued). "CD4+ T cell numbers and function determine the host susceptibility to infection." (PMID 21904545, 2011). "Both HIV and SIV cause rapid, persistent depletion of memory CD4+ T-cells soon after infection, suggesting early immunologic effects of infection may play a critical role in determining the subsequent disease." (PMID 22096538, 2011). "We next determined whether the increase in Treg cell numbers caused by IL-2Jc treatment during infection was the result of natural Treg cell expansion, or de novo conversion of naïve, Foxp3− CD4+ T cells into Treg cells." (PMID 21170302, 2010). "DC may transport HIV to regional lymph nodes where the virus can encounter CD4+ T cells, other targets susceptible to infection by R5 HIV." (PMID 21994649, 2010). "Alternatively, given the positive and negative selection forces that act on HTLV-1 replication throughout the duration of the infection in vivo, the mechanism underlying the clonal expansion of CD4+ and CD8+ cells might well have been selected in vivo." (PMID 20222966, 2010). "In pathogenic infections it is believed that in addition to infection and loss of short-lived T effector and T effector memory cells, damage to long-lived CD4+ Tcm populations that impairs the capacity to maintain immune cell homeostasis is a critical factor in progressive immunodeficiency." (PMID 20865163, 2010). "A delayed recovery of the CD4+ T-cell counts indicates an increased risk for subsequent infection." (PMID 20090932, 2010). "However these animals were found to be more susceptible to infection with C. neoformans, which resulted from defective induction of protective CD4+ T-cell responses." (PMID 21075040, 2010). "HAART initiated very early during infection could prevent the loss of CD4+ T cells from the gut and may delay the onset of the disease." (PMID 20868521, 2010). "However, CD4-expression alone is insufficient to confer susceptibility to infection with HIV, which also requires co-receptors, principally the chemokine receptors CXCR4 and CCR5." (PMID 20420700, 2010). "However, while activated CD4+ T cells are required to avoid the spread of MTB during infection, they can also cause severe inflammation with collateral tissue damage when not tightly controlled." (PMID 20544034, 2010). "The acute phase of human or simian immunodeficiency virus (HIV/SIV) infections is decisive as it is characterized by a quick and strong decrease of T CD4+ memory cells, particularly in the gut associated lymphoid tissue (GALT), and a rapid spread of the virus in all lymphoid tissues." (PMID 20868521, 2010). "This appears to be due to a negative effect of the activated CD4+ T-cells on VLP expression in Jurkat cells during the 48 h coculture infection, as the primary CD4+ T-cells (from various donors) were susceptible to infection with cell-free HIV-1 VLPs (D.M. and D.D., unpublished observation)." (PMID 20195464, 2010). "In pathogenic rhesus macaque infection, damage to the CD4+ T central memory (Tcm) subpopulation appears to play a central role in the inability of infected animals to replenish CD4+ T effector and effector memory (Tem) cells depleted by infection." (PMID 20865163, 2010). "However, gut mucosal lymphocyte infection and CD4+ T cell depletion occurs in natural host as well as pathogenic host infection." (PMID 20865163, 2010). "Notably, age at initial infection is an important determinant of survival, which in part underlies the effect of RNA and CD4: older patients have higher viral setpoints and hence faster CD4 decline and disease progression." (PMID 19536329, 2009). "In addition to the primary infection of susceptible populations of CD4+ T cells and monocytes/macrophages DCs can also support the integration of proviral DNA." (PMID 19674458, 2009). "Transmitted drug resistance has been associated with faster CD4 decline in the first year of infection, the spread of resistance mutations might thus also have contributed to the observed trend in the CD4 slopes." (PMID 19478880, 2009).
infection (continued). "While it is difficult to assess the pathogenic nature of CD4+ T cells due to their early role in infection, the symptomatic effector phase of ECM is believed to be precipitated by perforin-mediated apoptosis of brain endothelial cells by pathogenic CD8+ T cells." (PMID 19710907, 2009). "At first view this may seem counterintuitive since SIVmac239 infection of rhesus macaques is associated with high levels of chronic T cell activation and rapid loss of CD4+ T cell loss and progression to simian AIDS." (PMID 19358735, 2009). "This in turn may amount to a lower fraction of IM CD4+ T cells expressing CCR5 and lower cell turn-over, rendering the CD4+ T cell population less susceptible to infection." (PMID 19198651, 2009). "This suggests the higher amounts of PA receptor on NKT cells as compared to CD4+ T cells may only determine susceptibility to LT when there are very low amounts of LT at the earliest stages of infection." (PMID 19779559, 2009). "IFN-γ-deficient mice receiving immune CD4+ lymphocytes from vaccinated, wild type donor mice had improved survival after either infection, whereas wild type mice receiving immune CD4+ lymphocytes from IFN-γ-deficient, vaccinated donor mice did not have improved survival." (PMID 20041174, 2009). "Thus, following infection the frequency of CD4 and CD8 T cells specific for epitopes both encoded within the TB10.4 molecule, followed distinct patterns." (PMID 19529765, 2009). "Subsequent secreted proteins increase the expression of stimulatory receptors on B cells, which then interact with corresponding ligands on CD4+ T cells, allowing for either viral entry and the expression of viral proteins or the productive infection of susceptible CD4+ T cells." (PMID 19674458, 2009). "Recently also CD4+ T cells have been implicated in the early control of the infection." (PMID 19290047, 2009). "Alternatively, susceptibility to different infections at different CD4+ T cell counts could indicate a progressive decline in other arms of the adaptive immune system, especially CD8+ T cells, a decline that correlates with the decline in CD4+ T cells." (PMID 19943952, 2009). "Another explanation could be that the presence of ADCs causes immune activation that leads to increased infection of CD4 cells by HIV virus." (PMID 19630949, 2009). "To test whether production of β-chemokines by CD4+ T cells lowers their susceptibility to HIV infection, we measured cell-associated Gag DNA to assess the in vivo infection history of CMV-specific CD4+ T cells." (PMID 19876388, 2009). "Therefore, the loss of CD4 is associated with a productive infection in either endogenously or exogenously infected CD4+ T cell-derived blasts." (PMID 18617991, 2008). "To determine whether this pathway has a role in promoting steps in HIV replication, we examined infection of CD4+ T cells from mice deficient in PKC-θ or CARMA1." (PMID 18446227, 2008). "Strikingly, P5 inhibited CD4-dependent infection by T20-resistant R5-tropic HIV-1 variants." (PMID 18925934, 2008). "Similarly, mutation of glycosylation sites in SIVmac239 Env enhance CD4-independent infection mediated by CCR5." (PMID 18721458, 2008). "Similarly, CD4+ T-cells also showed a preferential susceptibility to infection with T-cell tropic strains in vitro." (PMID 18923697, 2008). "Infected individuals have a dramatically increased risk of infections with opportunistic pulmonary pathogens such as Mycobacterium tuberculosis or Pneumocystis jiroveci and this risk is inversely related to the number of circulating CD4+ T cells." (PMID 18802458, 2008). "Although this may suggest a risk in the increase of the viral reservoir due to infection of newly formed CD4+ T cells, it might also be indicative that rhGH induces elimination of HIV-1 from its reservoirs." (PMID 18976455, 2008).
infection (continued). "Thus, a positive correlation between CD4+ T cell decline and infection by syncytium-inducing HIV-1 or SIV-1 variants has been established in vitro and, more importantly, in vivo, in monkeys, humanized SCID mice and humans with AIDS." (PMID 18560558, 2008). "How the susceptibility of a cell to new infections declines with CD4 down-modulation remains unknown." (PMID 17967052, 2007). "Moreover, some individuals infected with nef-deleted HIV strains eventually experience CD4+ T-cell loss after many years of asymptomatic infection." (PMID 17888184, 2007). "The frequency of multiple infections depends not only on the viral load, but also on CD4 down-modulation induced by viral gene expression following the first infection of a cell, which lowers the susceptibility of the cell to further infections." (PMID 17967052, 2007). "For example, detection of increased percentages of “activated” CD4+ T cells in a tissue that has undergone massive CD4+ T cell depletion could be interpreted either as an immune response to the infection or as a selective loss of “resting” CD4+ T cells." (PMID 17147469, 2006). "In the virion-cell TAS, CD4 has been engaged, the heptad repeats of gp41 are exposed and the complex is kinetically predisposed to interact with coreceptor to complete the fusion event leading to infection." (PMID 16725045, 2006). "Future studies will validate this connection and attempt to determine whether changes in induction or maintenance immune suppression impacts frequency of CD4 T cell subtypes defined as conferring infection risk, as well as whether these subtypes might impact rejection risk." (PMID 40475763, 2025). "Importantly, treatment of rhesus macaques with pirfenidone at the time of SIV infection prevented lymphoid tissue fibrosis in vivo and was associated with preservation of CD4+ T cells in both lymph nodes and blood, while administration post-infection was less effective." (PMID 41573547, 2025). "Therefore, restoring the function of Tregs and CD4+ Trms may contribute to alleviating Th2 inflammation and reducing infection susceptibility in COPD patients." (PMID 40589761, 2025). "Environmental cues, such as infection route, expression of pathogen-associated molecular pattern molecules and antigen affinity and availability, are integrated to impact the generation of specialized CD4+ T helper (TH) cells that enable pathogen-specific adaptive immunity." (PMID 40926076, 2025). "Interestingly, there appears to be a time-based difference in the impact of these phenotypes on infection risk, with CD4 T cell frequency demonstrating a difference quite early post KTx while (~50–100 days) while the impact of CD4+EM+TIGIT appears to be later (~200–250 days)." (PMID 40475763, 2025). "Finally, in TB-susceptible mice, a higher proportion of CD4+ T-cells expressed both activation-associated and immune inhibition (checkpoint) markers, accompanied by functional CD4+ T-cell exhaustion at late stages of infection." (PMID 40873577, 2025). "However, shared programming across infections may underlie the establishment and survival of lung CD4 Trm in airway and interstitial niches." (PMID 39688906, 2024). "associated with a lower CD4+ T cell count might be due to deprivation of the immune cells that make the patients more vulnerable to getting infected with particular parasites and unable to clear them once the infection is established." (PMID 39597540, 2024). "Finally, we sought to examine whether RSTR CD4+ T cell phenotypes were associated with bacterial control by analyzing published NHP studies in which the Mtb burden was quantified after natural infection or experimental vaccination." (PMID 38997431, 2024). "Hence, we hypothesized that B cells dysfunction during acute infection stage may be caused by the combination of B cell exhaustion and reduced helper function of CD4+ T cells." (PMID 38898888, 2024).